GREP1 (glycine rich extracellular protein 1)
Description:
Could support the secretion of the hormone GDF15 in cancer cells.
Synonyms: LINC00514; G029442; LA16c-380H5.1; LA16c-380H5.3
Gene: Protein-coding gene on chromosome 16 (2,988,256 to 3,002,295, forward strand). Ensembl gene ENSG00000262152.
Subcellular location: Secreted
Gene Ontology:
Cellular component: extracellular region
Homologues: Orthologues: macaque GREP1 (81% identical), mouse Grep1 (47% identical), rat Grep1 (45% identical).
Diseases named in the same sentence as GREP1 in open-access papers:
GREP1 is named in the same sentence as 15 diseases in open-access papers, as found by Europe PMC text mining. Sharing a sentence is not in itself a finding about the gene and the disease. The quoted sentences say what the papers report.
breast carcinoma (3 papers, 2020 to 2024). "Deletion of GREP1 in 263 cancer cell lines resulted in a preferential loss of viability in certain cell lineages, particularly in breast cancer, highlighting its importance for cancer cell survival." (PMID 39333489, 2024). "Notably, the ORF G029442, now termed GREP1 (Glycine-Rich Extracellular Protein-1), encodes a secreted protein highly prevalent in breast cancer." (PMID 39333489, 2024).
GREP1 also shares sentences with these, for which no sentence is quoted: tumor (6 papers); cancer (4); gastric cancer (2); papillary thyroid cancer (2); esophageal squamous cell carcinoma (1); hepatoblastoma (1); liver cancer (1); liver disease (1); lung adenocarcinoma (1); lung carcinoma (1); metastatic tumors (1); non-small cell lung carcinoma (1); osteosarcoma (1); triple-negative breast carcinoma (1).